ALB (albumin)
Diseases named in the same sentence as ALB in open-access papers (continued):
Sharing a sentence is not in itself a finding about the gene and the disease.
preeclampsia (continued). "The study revealed that women with preeclampsia had higher values than healthy pregnant women in terms of age, weight, BMI, waistline, the proportion of previous cesarean sections, history of miscarriages, SBP, DBP, WBC, hematocrit, PLT, AST, ALT, albumin, total bilirubin, UA, urea, Mg, CI, and TSH." (PMID 38205084, 2024). "After adjustment for confounding factors (all variables not maintained in the equation), only the OxLDL/albumin ratio, lymphocyte percentage, UIC, K+/Mg2+ ratio, TSH, and FPG were identified as significant predictors of preeclampsia." (PMID 40282890, 2025). "During the third trimester, total free (total minus DBP- and albumin-bound) and bioavailable (total minus DBP-bound) maternal 25-hydroxyvitamin D3 (25(OH)D3) correlated with placental 25(OH)D3 in the third trimester, but this trend did not persist in preeclampsia." (PMID 36361738, 2022).
Hepatic steatosis (87 papers, 2012 to 2026). Steatosis is a term used to denote lipid accumulation within hepatocytes. "Another study was also found to cause hepatic steatosis at 0.25 and 0.5 mmoL/L and exerted a dose-dependent cytotoxic effect by inducing apoptosis and necrosis, and decreasing albumin production." (PMID 34961160, 2021). "While AAV encoding insulin fused to albumin exacerbated liver steatosis in several mice, AAV encoding insulin fused to apolipoprotein A-I reduced liver steatosis." (PMID 33679386, 2020). "The impact of albumin deficiency upon hepatic steatosis could be related to the reduced plasma FFA concentration, leading to a lower accumulation of both TAGs and CEs, the main storage forms of fatty acids." (PMID 37432201, 2023). "While further studies are needed to elucidate the underlying mechanisms, these findings offer new insight into the potential of albumin, either alone or in combination with other therapies, to reduce hepatic steatosis in MASLD." (PMID 40806286, 2025). "Existing studies have shown that the SII is consistent with increased urinary albumin excretion and hepatic steatosis, and it has been suggested as a biomarker for cardiovascular risk factors." (PMID 39319403, 2025). "The results indicated statistically significant differences in the concentrations of HSCRP, WBC, NE, and ALB among the various degrees of hepatic steatosis, with all p-values being less than 0.05." (PMID 40655480, 2025). "A notable effect of hepatic steatosis includes a reduction in serum albumin levels, indicative of compromised liver synthetic capacity, and an increase in plasma enzyme activity such as AST, aligning with observations made in this discourse." (PMID 38846787, 2024). "Some link specific systemic immune biomarkers (e.g., systemic immuno-inflammatory index [SII], neutrophil-to-albumin ratio [NPAR] and neutrophil-to-lymphocyte ratio [NLR]) to hepatic steatosis risk." (PMID 39296508, 2024). "Across the whole study collective, the estimated hepatic steatosis grade by echogenicity in the US images correlated with albumin, cholinesterase, liver transferases, ferritin, lipase, and lactate dehydrogenase." (PMID 36771265, 2023). "The estimated hepatic steatosis grade by hepatic fat fraction in the MRI correlated with albumin, cholinesterase, alkaline phosphatase, liver transferases, ferritin, lipase, and lactate dehydrogenase." (PMID 36771265, 2023). "The univariate analysis revealed that age, BMI, serum AST, ALT, TG, albumin levels, WC, the HSI, liver HU value, L–S HU value and the FLI were associated with hepatic steatosis." (PMID 36932382, 2023). "Albumin level was available only for two patients in the fatty liver group and NAFLD fibrosis (NFS) score indicated F3-F4 (advanced/sever) fibrosis in both of the two patients." (PMID 37840056, 2023). "Even when mice were obese and consumed high amounts of fat, albumin deficiency still led to lower plasma FFA levels, decreased hepatic steatosis, and improved glucoregulation." (PMID 37432201, 2023). "↑with hepatic steatosis, neutrophils infiltration and mortality in AH.Inversely correlated to albumin concentration." (PMID 35432367, 2022). "The development of hepatic steatosis was correlated with female sex, early postoperative serum albumin levels and pancreatic exocrine insufficiency at multiple linear regression analysis." (PMID 34067286, 2021). "Based on these considerations, we have developed a nanostructured plasmonic sensor based on commercial Blu-ray discs with integrated microfluidics for sensitive detection of albumin in cell culture supernatant from a 2D fatty liver disease model." (PMID 33334062, 2020). "In our multivariable analysis, high BMI, ALT, albumin, and high TG were the independent predictors of fatty liver changes in the Normal-GGT group, and high TG was the only independent predictor in the Abnormal-GGT group." (PMID 32650722, 2020).
Hepatic steatosis (continued). "Fatty liver disease, liver injury, total bilirubin, ALT, AST, LDH, CRP, GGT, platelet count, and albumin level were associated with more severe disease course." (PMID 33282888, 2020). "Our multivariable analysis identified BMI, ALT, albumin, and TG as independent predictors of fatty liver changes in the Normal-GGT group, and TG as the only independent predictor of fatty liver changes in the Abnormal-GGT group." (PMID 32650722, 2020). "This sensor allows the direct and label-free monitoring of albumin in a 2D fatty liver disease model under flow conditions using a highly-specific polyclonal antibody." (PMID 33334062, 2020). "The factors associated with fatty liver changes in the Normal-GGT group included body mass index (BMI), hemoglobin, alanine aminotransferase (ALT), albumin, triglyceride (TG), fasting blood sugar, and high-density lipoprotein levels." (PMID 32650722, 2020). "The strong binding of autoantibodies from obese and overweight patients to fructosylated-HSA-AGE points towards the involvement of modified lysine residues of albumin in the fatty liver disease." (PMID 31116779, 2019). "The findings lead to introduction of an informative biomarker panel including INS, PPARA, LEP, SREBF1, and ALB proteins related to the fatty liver disease." (PMID 28224024, 2016). "Whilst further studies are still required to investigate the mechanism that mediates these beneficial effects, our findings provide new insights toward the development of albumin, either alone or in conjunction with other therapeutic approaches, to reduce hepatic steatosis." (PMID 40806286, 2025). "Data on blood renal markers, albumin as measured by protein electrophoresis, urine protein:creatinine ratio, and urine glucose with paired serum glucose from nine white-bellied pangolins (Phataginus tricuspis) diagnosed with hepatic lipidosis at necropsy." (PMID 40530035, 2025). "Multivariate analysis demonstrated that BMI, serum transaminase, pre-albumin and disease duration could independently predict hepatic steatosis." (PMID 35413806, 2022). "Finally, for the MOD group, the blood pressure variables become correlated across the entire network, particularly with hepatic steatosis, hepatic enzymes (aspartate aminotransferase and alanine transaminase), and albumin." (PMID 35360235, 2022). "As a consequence, modifications on albumin levels might lead to unbound NEFA and their storage in the liver as triglycerides, which may cause fatty liver and aggravate the NEB." (PMID 35158566, 2022). "It is positively associated with albumin, liver enzymes (ALT, ALP, AST, GGT) and with hepatic steatosis, although whether this association is confounded by or mediated by LDL-C is still unclear." (PMID 34659352, 2021). "In the patients with fatty liver occurring after 12 months of TG, the serum levels of total protein and albumin chronologically decreased until 6 months and became significantly lower at 6 months after TG, compared with those in the patients without fatty liver." (PMID 34391390, 2021). "Development of a fatty liver caused reduction of ALP, TP, GLOB, and ALB levels." (PMID 29855491, 2018). "Treatment with SSB extract significantly increased ALP, TP, GLOB, and ALB levels suggesting that this treatment might improve fatty liver disease in the fish." (PMID 29855491, 2018). "INS, PPARA, LEP, SREBF1, and ALB are the introduced biomarker panel for fatty liver disease." (PMID 28224024, 2016). "We also studied whether the increased urine albumin excretion induced by higher serum fetuin-A levels was modified by improving hepatic steatosis and lipid metabolism disorder." (PMID 23710462, 2013). "In addition they had higher circulating alanine aminotransferase concentrations and lower circulating albumin and total protein than lean adolescents, possibly as a result of hepatocyte damage from fatty liver." (PMID 22682228, 2012).
Hepatic steatosis (continued). "This superior homeostatic control in females vs. males led to the discovery in the present study that the HFD for 8 weeks did not induce much hepatic steatosis in females, and thus it was difficult to test in this study if albumin deficiency would reduce liver fat accumulation." (PMID 39123208, 2024). "Considering that albumin is a predictive factor of NAFLD worsening, we also proceeded with a liver protein profile—total protein, albumin, and globulin—to check if the supplements would have any effect, and even whether in our mouse model of hepatic steatosis could be altered." (PMID 35326098, 2022). "When we compared our albumin blood data with values reported in cows with fatty liver degeneration, we found similar plasma concentrations in medium-intensity cases and greater and smaller values when compared with mild and severe hepatic steatosis, respectively." (PMID 34679884, 2021). "The aim of the study was to investigate the association between elevated serum fetuin-A and increased urine albumin excretion in obese rats, and whether increased urine albumin excretion was modified by improving hepatic steatosis and lipid metabolism disorder." (PMID 23710462, 2013). "Therefore, the increased urine albumin excretion is reversible by improving hepatic steatosis." (PMID 23710462, 2013). "Specifically, 0.35% GS can alleviate symptoms of hepatic steatosis; significantly reduce the levels of AST, TG, and MDA in serum; and increase the levels of ALB and GSH-Px (p < 0.05)." (PMID 41897887, 2026). "Before PS matching, significant differences were observed in the frequency of fatty liver (p < 0.001), PIVKA-II levels (p = 0.021), and serum levels of albumin (p = 0.003) between the groups." (PMID 40002160, 2025). "The risk factors included in the prediction model were bone mineral density at left femoral neck (LNBMD), hemoglobin (Hb), serum albumin (ALB), postprandial blood glucose (PBG), fatty liver disease (FLD), smoking and tea consumption." (PMID 38769526, 2024). "Univariate analysis showed hepatic steatosis, ALT, AST, GGT, ALB, GLB, PLT and the positivity of HBeAg were predictors of significant liver inflammation." (PMID 37770837, 2023). "In the trainingcohort, BMI, ALT/AST, albumin, triglycerides, CTL-S and CTL/S were found to be related to liver steatosis in Group one (p < .05, Spearman correlation analysis)." (PMID 37021007, 2023). "They stated that age, GGT, ALT, albumin, uric acid, glucose, LDL cholesterol, BMI, and AIP are independent factors that have a positive correlation with the progression of fatty liver disease, but AIP is the most notable independent factor among them." (PMID 37189890, 2023). "Age, GGT, ALT, ALB, DBIL, UA, FPG, LDL-c, BMI and AIP were independent factors positively correlated with the progress of fatty liver disease, among which AIP was the strongest factor." (PMID 32576204, 2020). "Furthermore, Lepr knockout nearly eliminated metformin’s benefits on liver steatosis, and even induced an increase in ALT and AST levels, and a decrease in albumin." (PMID 36737598, 2023). "BMI and serum AST, ALT, triglyceride (TG), albumin levels, and waist circumference (WC) were significantly higher in patients with hepatic steatosis than in those without hepatic steatosis." (PMID 36932382, 2023). "Blood albumin and total protein concentrations are trustworthy indicators of hepatic function and, collectively with blood AST and ALT levels and blood lipid profile, are closely related to the extent of hepatic lipidosis." (PMID 36851402, 2023). "In the multiple regression analysis, the SCD and serum albumin concentration were associated with the CAP, independent of pathological liver steatosis." (PMID 34341368, 2021). "In the Normal-GGT group, BMI, ALT, albumin, and TG levels were identified as independent predictors of fatty liver for multivariable analysis, whereas FBS or HDL was not identified as an independent predictor." (PMID 32650722, 2020).
Hepatic steatosis (continued). "Moreover, almost all biochemical profiles were significantly higher in participants with hepatic steatosis than those without hepatic steatosis (all p < 0.05), except platelet, albumin, and total bilirubin." (PMID 40027150, 2025). "The ALT, AST, ALP, HDL, BMI, USAT, and CAP are important variables related to hepatic steatosis, while age, gender, PLT, ALB, TP, DB, GLB, and LDL are not significant variables." (PMID 38395765, 2024). "There was a statistically significant difference in terms of gamma-glutamyl transpeptidase (GGT), triglyceride (TG), albumin, and NPAR between individuals with and without hepatic steatosis (GGT p<0.0001, TG p=0.0006, albumin p<0.0001, NPAR p=0.001)." (PMID 37525801, 2023). "Significant differences were observed in GGT, TG, albumin, and NPAR levels between individuals with and without hepatic steatosis." (PMID 37525801, 2023). "There was a statistically significant difference in terms of GGT (p<0.0001), TG (p=0.0006), albumin (p<0.0001), and NPAR (p=0.001) levels between individuals with and without hepatic steatosis." (PMID 37525801, 2023). "The individuals with fatty liver changes in the Normal-GGT group had significantly higher BMI, higher hemoglobin, ALT, albumin, FBS, and TG levels, and lower HDL than those without fatty liver changes." (PMID 32650722, 2020). "Regarding clinical metrics, hemoglobin, hematocrit, ALT, and albumin values were different between the two groups in no history of drinking group, whereas the AST levels of only subjects with fatty liver were higher than those of control subjects in history of drinking group." (PMID 34792476, 2021). "Although we have found a reduction in hepatic steatosis after the treatment, it was not reflected in improvement of the liver biochemistry and platelet count, since AST, ALT, AP, GGT, bilirubin, albumin and platelet number did not change compared to the baseline values." (PMID 27367724, 2016).
peritonitis (86 papers, 2012 to 2026). Inflammation of the peritoneum (tissue that lines the abdominal wall and covers most of the organs in the abdomen). "Previously reported risk factors for developing peritonitis include poor infection prevention care, exit-site infection, low serum albumin, higher Charlson comorbidity index (CCI) score, and lower clearance rate of urea nitrogen." (PMID 41001563, 2025). "Previous study found that serum albumin was an independent factor associated with peritonitis (p = 0.025)." (PMID 39944488, 2025). "In conclusion, mean and first-year mean albumin levels provide more determinative predictions for mortality, risk of peritonitis, and maintenance of residual renal functions in peritoneal dialysis patients compared to baseline albumin." (PMID 36762995, 2023). "In conclusion, mean and first-year mean albumin levels provide more predictive predictions for mortality, risk of peritonitis, and maintenance of residual renal functions in peritoneal dialysis patients than baseline albumin." (PMID 36762995, 2023). "Peritonitis in dairy cows is associated with increased albumin concentrations in peritoneal fluid and consequently an increased albumin peritoneal‐fluid‐to‐blood‐ratio and a decreased serum‐ascites albumin gradient." (PMID 36661389, 2023). "Although serum albumin and the risk of peritonitis have been extensively studied and it has been proven that low albumin increases the risk of peritonitis, increases in albumin have a protective effect on the risk of peritonitis." (PMID 36762995, 2023). "Findings of a systematic review demonstrated a strong association between the onset of peritonitis and a low serum albumin level at the onset of CAPD." (PMID 38021540, 2023). "Our aim in this study was to determine which albumin level gives more decisive predictions about increased mortality, peritonitis risk, and decreased RRF." (PMID 36762995, 2023). "In contrast, a lower fibrinogen to albumin ratio has predicted 28-day mortality in peritonitis-induced septic patients and is associated with poor overall survival in esophageal small-cell carcinoma patients." (PMID 35887976, 2022). "Our previous study demonstrated that patients with serum albumin < 3.5 g/dL had a 75% increased risk of peritonitis." (PMID 35690721, 2022). "We found that AID, HIS, and decreased levels of albumin were independently associated with the treatment failure of peritonitis, and FID also showed a trend related with the treatment failure of peritonitis." (PMID 35458175, 2022). "Univariate Cox regression analysis showed that factors including patient’s age, the level of serum albumin, and the type of peritoneal transport were associated with the onset of the first episode of peritonitis." (PMID 34233593, 2021). "The risk of peritonitis was increased by 6.8% for every 1 g/L decrease in the baseline serum albumin level." (PMID 34233593, 2021). "Our analysis demonstrated that a low level of baseline serum albumin was a significant risk factor for the first onset of PD-related peritonitis, which is consistent with previous reports." (PMID 34233593, 2021). "Consistently, our results showed that the risk of first-onset peritonitis increased by 6.8% for every 1 g/L reduction in the baseline serum albumin level." (PMID 34233593, 2021). "Other studies from China have also shown that the risk of developing early-onset peritonitis increases by 5.0% for every 1 g/L reduction in the serum albumin level." (PMID 34233593, 2021). "Other studies from Hong Kong and the United States have also revealed a 67% and 74% increase, respectively, in the risk of peritonitis for every 10 g/L reduction in the baseline serum albumin levels." (PMID 34233593, 2021). "Several studies associated low serum albumin at baseline PD initiation and change in follow-up period with increased risk of peritonitis." (PMID 34337034, 2021).